TNF (tumor necrosis factor)
Diseases named in the same sentence as TNF in open-access papers (continued):
Sharing a sentence is not in itself a finding about the gene and the disease.
Sepsis (continued). "Previous studies have shown that plasma sTim-3 plays an inhibitory role in sepsis patients, and is negatively correlated with TNF-α and IL-1218." (PMID 32714569, 2020). "In this study, we found disordered jejunal tissue structure in the sepsis model group, with decreased length of intestinal villi, reduced V/C values, reduced thickness of the mucosal layer, and increased levels of serum TNF-α and IL-1β." (PMID 33200654, 2020). "For many years it was thought that sepsis embodies an uncontrolled pro-inflammatory response driven by the production of pro-inflammatory cytokines such as tumor necrosis factor (TNF)-α and interleukin (IL)-1β in the first hours after infection." (PMID 32477337, 2020). "At the early stage of sepsis, activated macrophages release a large amount of pro-inflammatory cytokines such as TNF-α, IL-1β, IL-6 to resolve invading pathogens and injured tissues, playing pivotal role in host defense." (PMID 32415087, 2020). "Currently, anti-inflammatory treatment such as IL-1 receptor blockade, anti-IL-6, and anti-TNF are considered to be promising approaches in the early stage after the onset of sepsis, but it is too costly." (PMID 32153410, 2020). "Cytokines, especially TNF-α and IL-1, are important regulators of the immune response and their pathophysiological roles in sepsis have been widely studied." (PMID 32232117, 2020). "Recombinant GM-CSF therapy in immunosuppressed patients with sepsis can restore the HLA-DR expression and TNF production." (PMID 32197507, 2020). "The goal of the study was to evaluate a potential role for tumor necrosis factor alpha (TNF-α) genetic variability as biomarker in sepsis." (PMID 32171247, 2020). "We found that the PKM2 tetramer agonist TEPP-46 protects mice from endotoxemia and sepsis induced by LPS or CLP by reducing the release of TNF-α and IL-6." (PMID 33542713, 2020). "TNF-α is a proinflammatory cytokine mainly expressed in the initial hyperinflammatory stage of sepsis and is responsible for myocardial diastolic and systolic dysfunction." (PMID 32908632, 2020). "We therefore reasoned that inflammatory mediators, such as TNF-α, IL-1β, and IL-6, contained within the septic mesenteric lymph play an indispensable role in the lung injury induced by sepsis." (PMID 33145344, 2020). "Mice with sepsis showed an obvious intestinal barrier dysfunction with decreasing specific somatostatin receptor subtype (SSTRs), and increasing TNF-α, IL-6, and IL-10 in the ileum." (PMID 33376482, 2020). "TNF-α is an important cytokine involved in sepsis and inflammation and is a potential marker in the diagnosis of early and late onset neonatal sepsis." (PMID 32228505, 2020). "IL-10 is a crucial anti-inflammatory cytokine and immune support factor and also mediates the downregulation of proinflammatory cytokines such as TNF-α and IL-6 at the early stage of sepsis." (PMID 33376482, 2020). "Published concentrations of TNF-α, IL-1β, IL-17AF and IL-8 in infants with sepsis are inconsistent, with some studies reporting results similar to ours, and others reporting higher cytokine concentrations in septic infants." (PMID 32407417, 2020). "OB depletion is in part caused by a significant increase of inflammatory factors like IL-1β, TNFα, and G-CSF during the inflammatory phase of sepsis, making OBs a possible target for sepsis treatment." (PMID 32082321, 2020). "During sepsis, various cardiodepressive biomarkers such as tumor necrosis factor (TNF), interleukin- (IL-) 1β, and complement factor 5a (C5a) are released." (PMID 32410859, 2020). "Studies have found that the release of inflammatory cytokines, such as tumor necrosis factor (TNF-α) and interleukins (IL-1β and IL-6) increases, and promotes many immunopathological processes in sepsis, which are often referred to as “cytokines storm”." (PMID 33584285, 2020).
Sepsis (continued). "XBJ can stimulate an increase in the number of Treg cells in mice with sepsis and can reduce the levels of TNF-α and IL-6 in the serum to increase the survival rate of mice with sepsis." (PMID 32082396, 2020). "TNF-α is the most well-studied pro-inflammatory cytokine and has been shown to be involved in sepsis." (PMID 33344474, 2020). "Many research studies have identified the function of TNF-α and IL-1 in systemic inflammation, including both animal models of septic shock and in human sepsis trials." (PMID 33158114, 2020). "Collectively, these data suggest that the PKM2 tetramer agonist TEPP-46 protects mice from endotoxemia and sepsis induced by LPS or CLP by reducing the release of TNF-α and IL-6." (PMID 33542713, 2020). "Lastly, patients with severe COVID-19 pneumonia can trigger a state of sepsis that can induce the release of inflammatory cytokines such as IL-6, IL-8, TNF-α, among others that can promote the activation of a hypercoagulability disorder." (PMID 32841275, 2020). "Intravenous (IV) injection of ghrelin to the rat developing sepsis significantly reduced the elevated norepinephrine (NE) and tumor necrosis factor-alpha (TNF-α) level." (PMID 32565790, 2020). "Comparable to the time course of TNF in plasma, TNF concentrations in lung and liver tissue were already high at 4 h of sepsis duration and significantly decreased in liver tissue by 8 h after sepsis initiation." (PMID 33072121, 2020). "Sepsis-related mediators, such as endotoxin and the pro-inflammatory cytokines IL-1β, IL-2, IL-6, TNF-α, and IFN-β, have been shown to induce high expression of iNOS." (PMID 33123008, 2020). "Serum cytokines, including IL-6, IFN-γ, TNF-α, and IL-10, were elevated in the control groups and in SnPP-treated rats indicating sepsis." (PMID 32015027, 2020). "Serum levels of the inflammatory cytokines TNF-α and IL-1β were significantly increased (5-fold) in the sepsis group (p ≤ 0.05)." (PMID 33200654, 2020). "The results suggested that CLP-induced sepsis mice stimulated the secretion of pro-inflammatory cytokines (TNF-α and IL-6), but inhibited the regulatory immune pathway (lower levels of IL-10 and TGF-β)." (PMID 32423469, 2020). "The expression levels of THRIL, miR-19a and TNF-α in plasma from sepsis patients (n = 66) and healthy controls (n = 66) were measured using RT-qPCR assay." (PMID 32944003, 2020). "Anti-inflammatory agents such as interleukin (IL)-1 receptor antagonists and neutralizing antibodies against tumor necrosis factor (TNF) have been shown to be efficacious for the treatment of an animal model of sepsis." (PMID 32260474, 2020). "Studies indicate that proinflammatory cytokines/chemokines, such as TNFα, IL-6, IL-1β, or MCP-1, etc., released of from activated microglia are important mediators for sepsis-associated brain inflammation." (PMID 32070376, 2020). "Previous findings confirmed that the level of TNF-α, IL-1β, and IL-6 are elevated within 6 h in sepsis brain tissue and continually increased for 10 to 30 days." (PMID 32457609, 2020). "In accordance with the role of TNF‐α in these stimulation experiments, treatment of PBMCs from sepsis patients with zoledronate led an increased release of TNF‐α into the culture supernatant." (PMID 31606902, 2020). "In the patient with sepsis, IL-6 and TNF-α were significantly attenuated during H2 gas inhalation and increased after its discontinuation." (PMID 33041520, 2020). "It was reported that in mice, quercetin protects mice from LPS-induced sepsis by inhibiting proinflammatory cytokine TNF-α and IL-1β expression, NF-κB activation, and apoptosis." (PMID 32908632, 2020). "Several clinical studies have identified distinct patterns of elevated circulating cytokines in patients with sepsis and septic shock, and our finding of increased plasma TNF-α and IL-6 levels in the mouse model is consistent with these clinical data." (PMID 31959927, 2020).
Sepsis (continued). "In sepsis, endotoxin stimulates the synthesis and release of various pro-inflammatory cytokines and factors, including TNFα, IL-1β, IL-6, Fas ligand (FasL), granzymes, etc., mainly by mononuclear macrophages." (PMID 32457606, 2020). "Under acute inflammatory stresses, such as sepsis, PAMPs, cytokines (granulocyte colony-stimulating factor [G-CSF], IL-1, TNF-α), or both, stimulate large-scale de novo production of neutrophils from myeloid precursors in the bone marrow." (PMID 33613548, 2020). "In the liver, puerarin inhibited the transcription of inflammatory factor TNF-α, IL-6, and IL-1β and protected hepatocyte apoptosis in sepsis mouse models." (PMID 32457606, 2020). "By contrast, plasma TNF concentrations as an early responding pro-inflammatory cytokine started to trend down after 8 h of sepsis duration (mean 1,607 pg/ml, p < 0.001)." (PMID 33072121, 2020). "LVEDP,-dp/dtmax, cTnI, CK-MB, tumor necrosis factor-α, interleukin(IL)-6, and IL-1β were upregulated in the rat model of sepsis." (PMID 32578720, 2020). "VNS anti-inflammatory effects counteract lethal endotoxemia or polymicrobial sepsis in mice while reducing systemic TNF." (PMID 32848845, 2020). "Although TNF-α and IL-1β play major roles in the pathogenesis of sepsis in murine models, these cytokines have limited use as clinical markers for at-risk patients." (PMID 32826331, 2020). "In a clinical study, the levels of IL-1β, IL-6, TNF-α, etc., except for IL-10, were inhibited in the late phase of sepsis, while, in an animal study, the immune suppression status was attenuated with administration of the adenovirus Ade-HIF-1α." (PMID 32089644, 2020). "A wealth of research has corroborated that inflammatory cell infiltration and proinflammatory cytokines, including TNF‐α, IL‐6 and IL‐1β, play a vital role in the pathological process of sepsis." (PMID 32881263, 2020). "Ample evidence suggest that hemostatic changes in sepsis can be regulated by pro-inflammatory mediators such as TNF-α during the “cytokine storm”." (PMID 31281814, 2019). "Administration of 3-methyladenine (3-MA) (an autophagy inhibitor) attenuated the sepsis symptoms as well as the IL-6 and TNF-α production in a lethal model of murine sepsis." (PMID 31892110, 2019). "The secretion of proinflammatory cytokines, such as TNF-α and IL-1 (including IL-1α and IL-1β), in sepsis has been demonstrated in numerous studies." (PMID 31333903, 2019). "Post hoc comparisons showed that the expressions of IL-1β and TNF-α were markedly increased in sepsis mice at 24 h following CLP (all p < 0.01), whereas clenbuterol treatment markedly decreased these inflammatory mediators (all p < 0.01)." (PMID 31354429, 2019). "The elevation of IL-1 levels in patients with sepsis is less frequent than the increase in TNF-α levels." (PMID 30949497, 2019). "MRSA-mediated induction of the sepsis-associated molecule C-reactive protein (CRP), the proinflammatory cytokines IL-6, IL-1β, and TNF-α were also attenuated by Epi-1 treatment." (PMID 31835381, 2019). "In retrospective analyses, biomarker-based strategies identified heterogeneity in treatment effect in sepsis trials of recombinant human interleukin-1 receptor antagonist and anti-TNF-α antibody therapy." (PMID 31818332, 2019). "Neutrophils and monocytes from adults with sepsis have reduced activation and production of pro inflammatory cytokines (IL-1α, IL-6, TNF-α) in response to LPS." (PMID 31612119, 2019). "In early sepsis TNF-α, a pro-inflammatory cytokine released by monocytes and macrophages, is a marker of early sepsis and enhances the adaptive immune response." (PMID 31089920, 2019). "TNF-α levels were higher in the leptospirosis group as compared to sepsis and control groups in both the white and red pulps." (PMID 31114579, 2019). "In a mouse sepsis model, the ΔpfbA strain demonstrated significantly increased host mortality and TNF-α levels in plasma, but showed reduced bacterial burden in lung and liver." (PMID 31482074, 2019).
Sepsis (continued). "These TNFα antibodies had originally been prepared for clinical trials in human sepsis, which, however, entirely failed." (PMID 31694340, 2019). "The pro-inflammatory cytokine tumor necrosis factor (TNF), has long been considered as a top-candidate mediator in sepsis patients and animals." (PMID 31787972, 2019). "Post-treatment IL-6 and TNF plasma levels were decreased, suggesting an interesting strategy for sepsis." (PMID 31114571, 2019). "During the course of polymicrobial sepsis excessive production of proinflammatory cytokines, e.g., TNF or IL-1β, is dependent on IFNAR-mediated signaling." (PMID 31500303, 2019). "For example, interventions often studied by clinical trials included modifiers of the inflammatory response in sepsis such as anti-TNF, anti-IL1-Ra, anti-LPS, corticosteroids, IV immunoglobulins, and activated protein C." (PMID 31287020, 2019). "Other evidence has indicated that miR-23b plays crucial roles in the pathomechanism of sepsis by suppressing the production of inflammatory cytokines, including NF-κB, TNF-α, IL-6, IL-1β, and E-selectin." (PMID 31780861, 2019). "In sepsis, increased plasma levels of inflammatory cytokines, including TNF-α, IFN-γ, IL-13, participated in damaging the intestinal barrier function." (PMID 31354386, 2019). "HIF-1α deletion in myeloid cells led to reduced proinflammatory cytokines such as IL-1, IL-12, and TNF-α in the rat model of sepsis." (PMID 31093315, 2019). "As one of the most important proinflammatory cytokines, TNF-α can mediate a wide range of pathways such as both apoptosis and inflammation and has been defined as a major component in the pathogenesis of sepsis." (PMID 31093495, 2019). "Similar to the findings at 48 hpi, the majority of both WT and Myd88−/− mice had very high levels of IL-6, TNF-α, and IL-10, indicative of progressing sepsis." (PMID 30642901, 2019). "A common inflammatory response, also found during sepsis, is the increase of cytokine expression like TNFα and others." (PMID 31425567, 2019). "MONARCS was a phase III RCT performed on over 2500 patients with severe sepsis at 157 centers using the anti-TNFα antibody fragment, afelimomab." (PMID 31801287, 2019). "As expected, sepsis induced an acute increase in both inflammatory (TNFα, IL1β, IL-6) and anti-inflammatory (IL-10) plasma cytokine concentrations." (PMID 31248453, 2019). "Dysregulated expression of the cytokines TNF-α and IL-6 has been found to correlate with sepsis mortality." (PMID 31420571, 2019). "Sepsis induced a generalized up-regulation of both human and murine plasma cytokines (TNFα, IL-6, IL-10, IL-8/KC, MCP-1); it was additionally aggravated in P-DIE vs. P-SUR." (PMID 31297113, 2019). "Tumor necrosis factor-α (TNFα) is a major cytokine that is highly expressed in many diseased conditions, such as inflammatory diseases, sepsis, and cancer." (PMID 30818829, 2019). "We found sepsis-associated DVPs in genes important for immune response against infection and hyperinflammation such as IL1A and TNF." (PMID 31665078, 2019). "Yet, the levels of IL-6 and TNFα in serum are attenuated by alcohol in case of the sepsis group compared to the control sepsis group." (PMID 31739600, 2019). "Peripheral TNF, the key mediator of sepsis, is an acute phase response that initiates a cascade of cytokines." (PMID 30837977, 2019). "Studies have shown that the uncontrolled production of pro-inflammatory cytokines, such as TNF-α and IL-1β, plays a key role in the development of sepsis." (PMID 30967878, 2019). "During the recurrence and development of sepsis, the release of cytokines shows cascade effect, including the pro-inflammatory factors TNF-α, IL-1β and IL-623,24." (PMID 31432993, 2019). "In myocardium, TNF and IL-6 were significantly elevated in sepsis, TNF in both ventricles and IL-6 mostly in RV, while IL-1β, IL-18 and C5a were significantly higher in RV compared to LV after PAB (all p<0.05)." (PMID 31247004, 2019).
Sepsis (continued). "Additional humoral mediators responsible for coagulopathy include proinflammatory cytokines such as interleukin (IL)-1, IL-6, tumor necrosis factor-α (TNFα), elastase, cathepsin G and complement system proteins, as a systemic response in sepsis." (PMID 31121897, 2019). "In a prospective trial, sepsis patients with higher baseline interleukin-6 levels appeared more likely to respond to anti-tumor necrosis factor therapy." (PMID 31818332, 2019). "For example, in sepsis heparanase is upregulated by tumor necrosis factor-α (TNF-α) and induces shedding of the glycocalyx, thereby exposing the endothelial surface and adhesion molecules which facilitate neutrophil recruitment." (PMID 31110966, 2019). "In fact, lower mortality was observed in rats exposed to LPS and treated with a monoclonal antibody against TNF-α, and beneficiary effects were also observed for anti-IL-1β as well as anti-IL-6 antibody treatment in other experimental models of sepsis." (PMID 31075981, 2019). "More recently, a double-blind, placebo-controlled, phase IIa trial tested the safety and tolerability of AZD9773, a polyclonal anti-TNFα Fab in patients with severe sepsis." (PMID 31801287, 2019). "Attention was focused on the proinflammatory aspects of the immune response in sepsis, mostly because the typical early proinflammatory cytokines TNF and IL-1 were the first to be shown to induce organ failure in animals." (PMID 32082073, 2019). "TNF-α is a vital proinflammatory cytokine, and IL-10 is a vital anti-inflammatory factor; both cytokines are involved in the development of sepsis." (PMID 31354717, 2019). "We have shown that thoracic injury followed by CLP increased systemic levels of TNF-α; which is an important indicator of sepsis development." (PMID 31632392, 2019). "In order to evaluate the occurrence of sepsis-induced T-cell functional alterations in this cohort, we measured intracellular IL-2, TNFα, and IFNγ productions after ex vivo activation of T lymphocytes from patients and HVs." (PMID 30995946, 2019). "The idea of using compounds blocking TNF-α was further supported by the increased levels of TNF-α in the serum or tissues of patients with inflammatory diseases or infections, and in individuals affected by sepsis." (PMID 30941119, 2019). "For example, the administration of miR-146a was found to reduce proinflammatory cytokines (TNF-α, IL-1β, and IL-1α) and inflammatory edema in an LPS-induced model of sepsis in rats by targeting the TLR-4/NFκB pathway." (PMID 31671621, 2019). "In order to further investigate the effects of miR-106a on sepsis, we selected three cellular inflammatory factors TNF-α, IL-1β, IL-6 as representatives for research." (PMID 31432993, 2019). "Other in vitro models of renal tubular injury have used high concentrations of LPS and/or individual cytokines like IFN-γ and TNF-α, thereby limiting the relevance to the complex tubular epithelial milieu during sepsis." (PMID 31244655, 2019). "Increased cytokines, such as TNF-α and IL-6, are hallmarks of many human inflammatory states, including sepsis." (PMID 32082076, 2019). "In a cholestasis-induced liver injury model superimposed with sepsis, pretreatment with Hamp mitigated liver injury and reduced systemic IL-1, TNFα, and MCP-1." (PMID 31244655, 2019). "We performed the current study to explore potential predictive value of serum Tumor Necrosis Factor- (TNF-) like weak inducer of apoptosis (TWEAK) concentrations for 28-day mortality in patients with sepsis." (PMID 30733876, 2019). "Previous studies have shown that beta-blockers suppress inflammatory cytokine overproduction, among which the proinflammatory cytokine TNF-α, has been proven to induce lymphocyte cell death via the extrinsic apoptotic pathway in sepsis." (PMID 31885916, 2019). "The promoting effects of WISP1 on the release of TNF-α in macrophages have also been documented in sepsis-induced lung injury, suggesting it functions as a contributor of inflammation." (PMID 31660971, 2019).